LCN2 (lipocalin 2)
Diseases named in the same sentence as LCN2 in open-access papers (continued):
Sharing a sentence is not in itself a finding about the gene and the disease.
bacterial infection (continued). "Clinical studies have shown that lipocalin-2 levels rise rapidly during acute bacterial infection and inflammation in mammals." (PMID 40569986, 2025). "Some studies showed that LCN2 plays a protective role by sequestering iron from pathogens, thereby combating bacterial infections to some extent." (PMID 40025014, 2025). "LCN2 is known to act as a defense against bacterial infections by binding to iron-loaded bacterial siderophores and interfering with siderophore-mediated bacterial iron acquisition." (PMID 38673873, 2024). "Hepatocytes secrete extracellular LCN2, which serves as a protective mechanism against systemic bacterial infection." (PMID 39512683, 2024). "Lipocalin 2 (LCN2) is another glycoprotein upregulated in response to bacterial infection and tissue injury." (PMID 38999458, 2024). "LCN2 has been reported to modulate innate immunity, including the recruitment of neutrophils, and to protect against bacterial infections by sequestering iron." (PMID 37746070, 2023). "LCN2 was first considered to function in the innate immune response because of its up-regulation during bacterial infection." (PMID 35034646, 2022). "For example, LCN2 has been shown to mediate an innate immune response to bacterial infections by sequestering iron and is induced in the central nervous system of mice infected with West Nile virus encephalitis." (PMID 36399061, 2022). "LCN2 is first identified as an acute-phase protein produced by neutrophils during bacterial infections." (PMID 35308139, 2022). "LCN2 circulating levels increase under different pathological states, particularly kidney injury, bacterial infection, and inflammation as well as in people of advanced age." (PMID 35052623, 2022). "By binding to and sequestering iron-containing siderophores LCN2 can prevent bacteria iron uptake and alleviate bacterial infection." (PMID 35034646, 2022). "The first role assigned to LCN2 was part of the innate immune response to bacterial infection where LCN2 serves as an iron-containing siderophores sequester." (PMID 33799862, 2021). "During bacterial infection, neutrophils maintain iron homeostasis by releasing LCN2 and lactoferrin (LTF) to sequester free iron and protect the lung from oxidative stress induced by iron and HBA and HBB molecules." (PMID 33763112, 2021). "LCN2, an acute protein induced in response to bacterial infection, metabolic stress, or injury, has been proven to be a reliable biomarker of liver injury and inflammation." (PMID 34675931, 2021). "In line, the complete or hepatocyte-specific ablation of Lcn2 in mice resulted in increased sensitivity to bacterial infections." (PMID 34884961, 2021). "As such, elevated expression of LCN2 has been shown to be protective against bacterial infection because of its high affinity for siderophores." (PMID 34884961, 2021). "On the contrary, LCN2 showed protective effects in bacterial infections and animal models of liver injury." (PMID 34518636, 2021). "Lipocalin-2 (LCN2) is a secreted glycoprotein involved in transporting hydrophobic ligands across the cell membrane, modulating the immune response during bacterial infection, and promoting epithelial cell differentiation and iron homeostasis." (PMID 34445288, 2021). "LCN2 plays a crucial role in various cellular responses, such as in the defense against bacterial infections through the regulation of iron accumulation in the cell, inflammatory signaling, and apoptotic signaling." (PMID 33945675, 2021). "LCN2 plays an important role in innate immune responses against bacterial infections by sequestering iron-containing siderophores." (PMID 34518636, 2021). "Lipocalin 2 (LCN2), an acute-phase protein produced during acute liver injury, plays an important role in the innate immune response against bacterial infection via iron scavenging." (PMID 34518636, 2021). "Bacterial infection leads to enhanced expression of LCN2 to protect the intestinal barrier function." (PMID 34884961, 2021).
bacterial infection (continued). "Lcn2 is produced by hepatocytes and neutrophils; extracellular Lcn2 secreted by hepatocytes limits systemic bacterial infection, whereas neutrophils carry the Lcn2 protein to local sites and protect against local bacterial infection." (PMID 32365611, 2020). "NGAL, also known as lipocalin 2 (Lcn2), binds siderophores, conferring it an important role in the innate immune response against bacterial infections." (PMID 33198361, 2020). "Targeted disruption of Lcn2 gene has demonstrated its essential role in the early stages of the innate immune response to bacterial infection." (PMID 31781104, 2019). "In this study, we found that there were more bacteria loaded in the blood and liver of Lcn2−/− mice, which indicated that Lcn2−/− mice succumb to bacterial infection more easily." (PMID 31781104, 2019). "A decade ago, the production and expression of Lcn2 in the intestinal epithelium was demonstrated in a rhesus macaque model of bacterial infection and by administration of indomethacin in mice." (PMID 31375129, 2019). "LCN2 acts as an acute-phase-protein during bacterial infections and exhibits a unique antimicrobial mechanism." (PMID 31091692, 2019). "Lcn2 is required for animals to mount a proper host defense to bacterial infection by maintaining normal neutrophil maturation and modulating the function of macrophages." (PMID 31781104, 2019). "LCN2 is mainly synthesized and secreted from neutrophil and plays a role in the innate immune response to bacterial infection by sequestrating iron from pathogens." (PMID 31500632, 2019). "In this regard, Lcn2 plays an essential role in the innate immune response against bacterial infection." (PMID 31781104, 2019). "The significance of the inverse regulation of Lcn2-R and Lcn2 as a protective measure in the context of normosmotic conditions and/or bacterial infection is discussed." (PMID 30404645, 2018). "The localization of Lcn2-R in the inner medulla is intriguing considering local bacterial infections trigger toll-like receptor-4 (TLR-4)-mediated secretion of the bacteriostatic Fe3+-free (apo-)Lcn2." (PMID 30404645, 2018). "LCN2 is a small secreted glycoprotein from the lipocalins family proteins that is important in the protection against bacterial infection and in the modulation of oxidative stress." (PMID 29321030, 2018). "Downregulation of Lcn2-R as well as upregulation and increased secretion of Lcn2 induced by an isosmotic interstitium and/or LPS, which may be encountered during inflammation-associated hyperperfusion and/or late reparative stages of bacterial infection, could offset these detrimental consequences." (PMID 30404645, 2018). "Lipocalin 2 binds to siderophores and activates the innate immune system against bacterial infection." (PMID 28934943, 2017). "Since bacterial infection first occurred in the gastrointestinal tract, we focused on the expression of Lcn2 in various intestinal segments." (PMID 29029438, 2017). "In the current study, we examined the role of Lcn2 in intestinal defense against bacterial infection and the mechanism of its regulation in a piglet model of E. coli K88 infection." (PMID 29029438, 2017). "In this regard, Lcn2/NGAL plays an essential role in the innate immune response against bacterial infection." (PMID 27734904, 2016). "During bacterial infection, the expression of LCN2 has been proved to be upregulated in several tissues such as liver, diverse mucosal tissues, lung, and epithelial tissue." (PMID 27729871, 2016). "All these results confirm the induction and the early detection of lipocalin 2 in the CSF after bacterial infection in mice." (PMID 24885531, 2014). "Lcn2 (Lipocalin 2) is important in the defense against bacterial infection by interfering with bacterial iron acquisition." (PMID 23951329, 2013).
bacterial infection (continued). "The dramatic decrease in lipocalin-2 levels, identified in both the plasma and urine of LRRK2 knockout rats, is a peculiar finding as lipocalin-2 has been identified to be a critical component in innate immunity to bacterial infection." (PMID 23799078, 2013). "Our data suggest possible inter-relationships between pathways involving resistin, cytotoxic T cell activity and lipocalin-2, and a significant role for these proteins in the host defence against bacterial infection." (PMID 22559298, 2012). "Based on our data, we suggest that Lcn2 will play a crucial protective role in models of mucosal extracellular bacterial infection where neutrophils recruitment is important for clearance of the pathogen." (PMID 23185529, 2012). "We have previously demonstrated a strong up-regulation of lipocalin 2 in human bronchial epithelium in connection with bacterial infections." (PMID 20633248, 2010). "Lcn2 knockout mice are more susceptible to bacterial infections, with increased mortality rates due to the lack of LCN2’s bacteriostatic activity and decreased immunological function." (PMID 41487016, 2026). "SLC22A17 is a cell surface receptor for Lipocalin 2, an antibacterial protein that acts by sequestering iron during bacterial infection and has recently been reported to be involved in various pathophysiological conditions in various organs and tissues, including the heart and brain." (PMID 38969939, 2024). "Lcn2, also called neutrophil gelatinase-associated lipocalin (NGAL), induces CXCR2 and has been shown in mice to be important for promoting neutrophil migration and protective against bacterial infection." (PMID 38567642, 2024). "Studies in Lcn2 null mice have shown increased sensitivity to bacterial infections." (PMID 38673873, 2024). "Moreover, and more intriguingly, LCN2 has been suggested to mediate innate immune responses to bacterial infection by sequestrating iron, whereas both iron homeostasis, as well as microbiome regulation, have been linked with IPF pathogenesis." (PMID 37746070, 2023). "LCN2 is produced during the innate immune response to bacterial infection as a bacteriostatic factor, and we here demonstrated that interactions between LCN2 and NLRP3 could promote neuroinflammation in the early phase of SCI." (PMID 37240031, 2023). "Lipocalin-2 (LCN2), also known as neutrophil gelatinase-associated lipocalin (NGAL), is an antibacterial secreted protein of the lipocalin family involved in the control of various biological processes, such as responding to bacterial infection, cell migration, and innate immunity." (PMID 37240031, 2023). "Lipocalin 2 (Lcn2), which is important in controlling bacterial infection in mice and could be induced by the IL-20 subfamily was upregulated." (PMID 38390396, 2023). "LCN2 mediates the innate immune response to bacterial infection by sequestering iron." (PMID 36443881, 2022). "In our study, we showed that untreated Lcn2-/- mice were extremely prone to bacterial infections." (PMID 34884961, 2021). "Interestingly, lipocalin 2 in humans is synthesized by immune cells when facing bacterial infections and acts to inhibit bacterial growth by disrupting the iron that the bacteria would use." (PMID 34988032, 2021). "LCN2 is an antibacterial protein that acts by sequestering iron during bacterial infection and has recently been reported to be involved in various pathophysiological conditions in various organs and tissues, including the heart, lung, liver, kidney, and brain." (PMID 33945675, 2021). "Suppressing the expression of Lcn2 followed by a bacterial infection may be harmful or lethal in ank/ank mice which already have subclinical gut inflammation." (PMID 32188494, 2020). "The protective, antimicrobial action of Lcn2 is related to its binding to iron-loaded bacterial siderophores leading to their sequestration and, in consequence, iron-depletion as part of the acute-phase response to bacterial infection." (PMID 33105802, 2020).
bacterial infection (continued). "Whereas, the ability of Lcn2 to sequester iron is well-described, the role of Lcn2 in regulating immune cells during bacterial infection remains unclear." (PMID 31781104, 2019). "The sequestration of iron by LCN2 could play a protective role in the innate immune response against bacterial infections and may be involved in the initiation of apoptosis." (PMID 30050936, 2018). "Accordingly, the mice lacking Lcn2 are more susceptible to bacterial infection compare to wild type mice." (PMID 27254317, 2016). "Lcn2 has been known to play a key role in innate immunity and protect against bacterial infection." (PMID 24818605, 2014). "LCN2 is a part of the acute innate immune response to bacterial infection." (PMID 24885531, 2014). "Lcn2 has emerged as a key factor in the host response to bacterial infection." (PMID 21943033, 2011). "Further supporting a role of Lcn2 as a bacteriostatic agent, mice lacking Lcn2 are markedly more susceptible to bacterial infection compared with wild type mice." (PMID 21943033, 2011). "Therefore, lipocalin-2 exerts bacteriostatic actions and appears to play an important role in innate immunity and immune response to bacterial infections." (PMID 21143924, 2010). "Moreover, Lcn2 is one of the components of the innate immune response against bacterial infection." (PMID 34917064, 2021). "However, the precise role of Lcn2 in bacterial infection remains to be elucidated." (PMID 31781104, 2019). "Also, LCN2 is an antimicrobial protein; it has been reported that LCN2 may play a key role in the innate immune response to bacterial infection." (PMID 31467617, 2019). "Therefore, the up regulation of antimicrobial proteins in cluster 5 like CAMP and Lcn2 observed after IR could be related to protection against bacterial infection and modulation of oxidative stress." (PMID 30555831, 2018). "AGP, LCN2, LCN1, and C8G (which generate a functional membrane attack complex) control bacterial infections by scavenging iron-containing siderophores." (PMID 38673873, 2024). "Consequently, mice lacking Lcn2 are highly susceptible to bacterial infections." (PMID 34884961, 2021). "To mimic bacterial infection by UPEC, we applied LPS to mIMCD3 cells in a hyperosmotic environment, which has been shown to elicit secretion of Lcn2 in kidney medulla." (PMID 30404645, 2018). "It is possible that Lcn2/NGAL system is evolutionarily designed to selectively remove the iron-binding siderophore and polyphenols so that immune system can clear the bacterial infections." (PMID 27254317, 2016). "Lipocalin 2 (LCN2) is an inducible protein secreted by a variety of cell types in the brain, liver, and uterus that mediates intercellular communication, innate immune responses to bacterial infections, and iron homeostasis." (PMID 38283681, 2023). "Similar to Vero, a number of cytokines associated with bacteria were identified in Huh7 cells, such as lipocalin 2 (LCN2), which inhibits bacterial infection, was upregulated, whereas C-C motif chemokine ligand 26 (CCL26), a chemoattractant for eosinophils and basophils, was downregulated." (PMID 34899651, 2021). "An enhanced luminal level of lipocalin-2 that is primarily secreted by neutrophils was subsequently found in the absence of NLRP12 as early as day 8 after bacterial infection." (PMID 30559449, 2018). "Other biomarkers with one to two studies showing statistically significant differences in expression levels in bacterial infection patients compared to non-bacterial infection patients include LBP, LCN-2, lactoferrin, sPLA2, D-Lactate in CSF, EDA-FN, FN, and soluble CD14." (PMID 27486746, 2016). "In addition to its regulatory role in the expression of S100A9 and lipocalin-2 as we reported here, whether IL22 also contributes to urothelium defense mechanisms against bacterial infection by regulating HUC production of HA or HUC expression of TLR4/CD14 remains to be elucidated." (PMID 25354343, 2014).
kidney (70 papers, 2013 to 2026). "While enhanced levels of iron-free Lcn-2 from TEC were mainly associated with kidney injury markers at 24 h of CLP-induced kidney injury, increased levels of MΦ-derived, iron-loaded Lcn-2 was associated with recovery markers." (PMID 33065981, 2020). "Lrp2 KO mice had significantly increased transcript levels of acute kidney injury markers, kidney injury molecule-1 (KIM-1; Havcr1), and neutrophil gelatinase-associated lipocalin (NGAL; Lcn2), compared with control mice." (PMID 38984983, 2024). "Serum LCN2 levels were positively correlated with both the abdominal aorta calcification (AAC) score (r = 0.5875, p < 0.0001) and the serum calcium concentration (r = 0.2384, p < 0.01)." (PMID 39613734, 2024). "Lipocalin 2 (Lcn2) is a multifunctional protein involved in inflammation, acute kidney injury, and bone and muscle pathophysiology." (PMID 35055145, 2022). "The inverse correlation between SIRT2-C/EBPβ-LCN2 axis expression and alcoholic liver injury in clinical samples further strengthen this novel mechanism." (PMID 34642310, 2021). "Expression levels of acute kidney injury markers Kim1 and Lcn2, and cytokines Ccl2 and Cd68, were lower in the cisplatin-injected Dpep1+/− mice when compared to wild-type littermates." (PMID 34426578, 2021). "In the mouse model of transient middle cerebral artery occlusion (tMCAO), LCN2 expression in the brain was analyzed by immunohistochemistry and correlated to cellular nonheme iron deposition up to 42 days after tMCAO." (PMID 27152948, 2016). "LCN2 has been established as a biomarker of acute kidney injury and a prognostic factor in chronic kidney disease." (PMID 27152948, 2016). "Although some increased LCN2 at the ischemic site is thought to be derived from infiltrating neutrophils after transient middle cerebral artery occlusion 82, 83, we cannot confirm that the LCN2 observed in the infiltrating neutrophils is brought in from the periphery." (PMID 40083945, 2025). "Together, hepatic LCN2 plays a protective role in alcoholic liver injury." (PMID 34642310, 2021). "Experimental aldosterone-induced kidney injury is accompanied by augmented expression of lipocalin-2 in visceral adipose tissue, and selective and specific deletion of lipocalin-2 only in adipose tissue—but not in the kidney—counteracts renal inflammation and fibrosis." (PMID 41668130, 2026).